DCUN1D1 (defective in cullin neddylation 1 domain containing 1)
Diseases named in the same sentence as DCUN1D1 in open-access papers:
DCUN1D1 is named in the same sentence as 31 diseases in open-access papers, as found by Europe PMC text mining. Sharing a sentence is not in itself a finding about the gene and the disease. The quoted sentences say what the papers report.
cervical cancer (5 papers, 2016 to 2022). A primary or metastatic malignant neoplasm involving the cervix. "Then, we analyzed the association between DCUN1D1 expression and clinicopathologic features, and the results revealed that the expression of DCUN1D1 was significantly higher in cervical cancer tissues than in adjacent normal cervical tissues (P= 0.017)." (PMID 27285984, 2016). "3q26-amplified cervical cancers are theoretically a good candidate to consider, as they possess amplifications of DCUN1D1, a regulator of CRLs-mediated ubiquitination." (PMID 34436017, 2021). "MiR-218 was also found to inhibit epithelial-mesenchymal transition (EMT), migration, and invasion by targeting SFMBT1 and DCUN1D1, and was downregulated in cervical cancer." (PMID 31310241, 2019). "DCUN1D1 isotype control staining was performed on cervical cancer tissue in order to assure specificity." (PMID 27285984, 2016). "In this study, we revealed that DCUN1D1 is upregulated in human cervical cancer and is positively correlated with cervical cancer grade and clinical stage." (PMID 27285984, 2016). "In accordance with these results, we found a clear decrease in endogenous SFMBT1 and DCUN1D1 protein expression in cervical cancer cells when miR-218 was overexpressed." (PMID 27285984, 2016). "The overexpression of SFMBT1 induced EMT and increased the migration and invasiveness of cervical cancer cells, while the overexpression of DCUN1D1 increased the migration and invasiveness of these cells, but did not induce EMT." (PMID 27285984, 2016). "The results showed that DCUN1D1 expression by immunostaining is negatively correlated with miR-218 expression in cervical cancer tissues (P<0.001)." (PMID 27285984, 2016). "An inverse correlation was observed between the expression of miR-218 and DCUN1D1 protein in cervical cancer tissues." (PMID 27285984, 2016). "This suggests that the decrease in SFMBT1 and DCUN1D1 expression is required for the decrease in the invasiveness of miR-218-overexpressing cervical cancer cells." (PMID 27285984, 2016). "To study the relationship between miR-218 and its target genes, we detected the expression of DCUN1D1 in another cervical cancer tissue microarray." (PMID 27285984, 2016). "The results showed that knockdown of SFMBT1 or DCUN1D1 inhibited invasion of cervical cancer cell similarly as those that were observed in miR-218 overexpression treatment." (PMID 27285984, 2016). "Our results imply that DCUN1D1 may play a vital role in the inhibitory effects of miR-218 on cervical cancer metastasis." (PMID 27285984, 2016). "Moreover, we identified SFMBT1 and DCUN1D1, which are responsible for the metastasis of cervical cancer, as the direct functional targets of miR-218." (PMID 27285984, 2016). "Interestingly, we found that DCUN1D1 was targeted by miR-218 and knockdown of DCUN1D1 significantly decreased the invasiveness of cervical cancer cells." (PMID 27285984, 2016). "To determine whether SFMBT1 and DCUN1D1 serve as critical mediators in the role of miR-218 on cervical cancer, we knocked down SFMBT1 and DCUN1D1 by the application of synthetic siRNA in SiHa and HeLa cells." (PMID 27285984, 2016). "Here, we found that HPV16 E6 promotes EMT and enhances the invasiveness of cervical cancer cells, which is consistent with the effects of SFMBT1 and DCUN1D1 and is contrary to the effect of miR-218 on cervical cancer metastasis." (PMID 27285984, 2016). "Taken together, our results revealed that HPV16 E6 promoted EMT and invasion in cervical cancer via the repression of miR-218, while miR-218 inhibited EMT and invasion in cervical cancer by targeting SFMBT1 and DCUN1D1." (PMID 27285984, 2016). "Interestingly, a homologous to DCUN1D1 gene, DCUN1D5 is located at 11q22 and is amplified in 8.1% of samples in cervical cancer TCGA cohort." (PMID 34436017, 2021).
cervical cancer (continued). "In total, we suggest that HPV16 E6 may promote the metastasis of cervical cancer by repressing miR-218 expression, and then promote the expression of SFMBT1 and DCUN1D1." (PMID 27285984, 2016). "Importantly, HPV16 E6 downregulated the expression of miR-218 in cervical cancer, while miR-218 rescued the promotion effect of HPV16 E6 on the expression of SFMBT1 and DCUN1D1." (PMID 27285984, 2016).
prostate carcinoma (4 papers, 2014 to 2023). A carcinoma that arises from epithelial cells of the prostate gland. "After demonstrating that DCUN1D1 elicits a pivotal role in prostate cancer development, we performed a deeper analysis to explore in more detail the mechanism underlying the biological activity of DCUN1D1." (PMID 37566052, 2023). "DCUN1D1 plays a role in tumourigenesis and progression and has been associated with poor prognosis in gliomas, lung, cervical cancer, laryngeal squamous cell carcinoma, colorectal, head and neck and prostate cancers." (PMID 37566052, 2023). "Although established as an oncogene in a variety of squamous cell carcinomas, the precise role of DCUN1D1 in prostate cancer (PCa) has not been previously explored thoroughly." (PMID 37566052, 2023). "Importantly, DCUN1D1 was also higher expressed in prostatic cancer samples with perineural invasion as compared to adjacent normal tissue." (PMID 37566052, 2023). "Defective cullin neddylation 1 domain‐containing 1/squamous cell carcinoma‐related oncogene (DCUN1D1/SCCRO) is a ring-finger domain ubiquitin E3 enzyme that is involved in the growth and metastasis of malignancies such as colorectal, glioma and prostate cancers." (PMID 37554324, 2023).
lung squamous cell carcinoma (3 papers, 2016 to 2018). "Squamous Cell Carcinoma-related Oncogene SCCRO (also known as DCUN1D1) is a part of E3 ligase complex (Cul-1-ROC1-SCCRO) is associated with the development of primary of squamous cell carcinoma of the lung with malignant phenotypes." (PMID 29541423, 2018). "Increased DCUN1D1 promotes regional lymph node and brain metastases, and decreases the survival of patients with lung squamous cell carcinoma." (PMID 27285984, 2016).
ovarian carcinoma (3 papers, 2014 to 2024). A malignant neoplasm originating from the surface ovarian epithelium. "DCUN1D1 is an E3 ligase of the neddylation pathway and has been reported to be upregulated and associated with aggressive phenotypes and poor clinical outcomes in several types of cancer, particularly head and neck, lung, cervical and ovarian cancer as well as gliomas." (PMID 37566052, 2023).
squamous cell carcinoma (3 papers, 2019 to 2023). A carcinoma arising from squamous epithelial cells. "Similarly, miR-195 inhibits cell proliferation, colony formation, migration, and invasion, promoting cell cycle arrest and apoptosis by directly targeting DCUN1D1, known as a squamous cell carcinoma-related oncogene." (PMID 35406495, 2022).
head and neck cancer (2 papers, 2014 to 2021). A primary or metastatic malignant neoplasm affecting the head and neck. "A significant number of genes were amplified in greater than 30 percent of cancer patients, including DCUN1D1 (43% of lung squamous cancers), FADD and PPFIA1 (∼30% of head and neck cancers), and PRKCI (36% of lung squamous cancers)." (PMID 24874471, 2014).
Infertility (2 papers, 2019 to 2023). "In addition, these aberrant spermatozoa indicated the presence of abnormal intercellular bridges, which were probably responsible for specific infertility and inability to release mature spermatozoa of DCUN1D1-/- mice." (PMID 36980830, 2023). "In this study, we sought to determine the basis of infertility in male DCUN1D1-/- mice." (PMID 30653527, 2019). "Targeted inactivation of DCUN1D1 in mice results in male-specific infertility." (PMID 30653527, 2019). "Infertility in DCUN1D1-/- mice is secondary to primary defects in spermatogenesis." (PMID 30653527, 2019). "In addition, testosterone levels were normal in DCUN1D1-/- mice, suggesting that infertility was not caused by hormonal deficiencies (n = 8)." (PMID 30653527, 2019).
female infertility (1 paper, 2019). Diminished or absent ability of a female to achieve conception. "Interestingly, knockout of DCUN1D1 in Drosophila results in partial female infertility, likely reflecting similarities between spermatogenesis in mice and oogenesis in flies." (PMID 30653527, 2019).
Globozoospermia (1 paper, 2019). Any structural anomaly of the acrosome resulting in a round sperm head. "Tubulin staining of mature spermatozoa in DCUN1D1-/- mice also revealed multiple abnormalities, including the presence of globozoospermia, macrocephaly, and multiple flagella." (PMID 30653527, 2019). "Spermatozoa in DCUN1D1-/- mice had multiple abnormalities, including globozoospermia, macrocephaly, and multiple flagella." (PMID 30653527, 2019).
lung adenocarcinoma (1 paper, 2014). A carcinoma that arises from the lung and is characterized by the presence of malignant glandular epithelial cells. "We identified the neddylation ligase DCUN1D1 as a putative amplified cancer driver that was amplified in over 40% of lung adenocarcinomas and squamous cancers." (PMID 24874471, 2014).
lung carcinoma (1 paper, 2016). "It was recently reported that DCN-like protein 1, encoded by the DCUN1D1 gene, is amplified in several types of cancer as an oncogene and was identified as a molecular marker of lung cancer patients at high risk for brain metastasis." (PMID 26883469, 2016).
male infertility (1 paper, 2024). The inability of the male to effect fertilization of an ovum after a specified period of unprotected intercourse. "Deletion of DCUN1D1, a component of the E3 for neddylation in mice results in retention of excess cytoplasm, failure of individualization and male infertility." (PMID 38421455, 2024).
metastatic prostate carcinoma (1 paper, 2023). A carcinoma that arises from the prostate gland and has spread to other anatomic sites. "In metastatic prostate cancer, elevated DCUN1D1 expression was retained." (PMID 37566052, 2023).
non-small cell lung carcinoma (1 paper, 2023). A group of at least three distinct histological types of lung cancer, including non-small cell squamous cell carcinoma, adenocarcinoma, and large cell carcinoma. "Upregulation of the expression of DCUN1D1 significantly increased the levels of PD - L1 protein in non-small cell lung cancer cells." (PMID 37554324, 2023). "A recent study revealed the oncogenic mechanism of DCUN1D1 in non-small cell lung cancer." (PMID 37554324, 2023).
cancer (20 papers, 2014 to 2026). A tumor composed of atypical neoplastic, often pleomorphic cells that invade other tissues. "DCUN1D1 overexpression has been implicated in the proliferation and migration of cancer cells." (PMID 37566052, 2023). "The selective effects of DCUN1D1 in neddylation, combined with an “oncogene addiction” phenotype associated with its overexpression in human cancers, suggest that DCUN1D1 may be an excellent therapeutic target." (PMID 30653527, 2019). "DCUN1D1 clearly functions as an oncogene in PCa and dysregulation in its expression is detrimental to cancer." (PMID 37566052, 2023). "Although it has been described as an oncogene in different types of cancers, the precise function of DCUN1D1 and its mechanism of action are not clearly understood." (PMID 37566052, 2023). "Remarkably, our analysis indicated cancer, cellular immune response, cell growth, proliferation and development as the most enriched dysregulated functions upon DCUN1D1 inhibition." (PMID 37566052, 2023). "While upregulated in PCa, DCUN1D1 is involved in crucial cancer hallmarks such as proliferation, migration, apoptosis and tumour growth." (PMID 37566052, 2023). "The implications of this down-regulation for processes involving CRL-associated ubiquitination would be broad and far reaching for cancer cells with DCUN1D1 amplifications, including cervical squamous carcinomas." (PMID 34436017, 2021). "DCUN1D1 (Defective in Cullin Neddylation 1 domain containing 1, alternatively named SCCRO-Squamous Cell Carcinoma-Related Oncogene) is another cancer-associated gene located at 3q26." (PMID 34436017, 2021). "In the Genomics of Drug Sensitivity in Cancer (GDSC) database, part of the 3q26 locus, including SOX2 and DCUN1D1 genes, is identified as a recurrent copy-number alteration in the pan-cancer analysis (feature cnaPANCAN246 in the database)." (PMID 34436017, 2021). "Ubiquitin-like ligase DCUN1D1 is involved in the malignant transformation of squamous cell lineage and has been identified as a potential cancer driver gene." (PMID 32613561, 2020). "DCUN1D1 is recognized as an oncogene and is overexpressed in many types of malignant tumors that leads to a series of diseases including cancers." (PMID 30833362, 2019). "Increasing evidence revealed that DCUN1D1 is overexpressed in many types of malignant tumors and regulates tumor progression, chemosensitivity, angiogenesis and metastasis." (PMID 27285984, 2016). "DCUN1D1 is an E3 ubiquitin ligase complex subunit with potential cancer driver activity, which we further validated with shRNA knockdown (below)." (PMID 24874471, 2014). "We found that DCUN1D1-amplified cancer cell lines exhibited decreased cell proliferation/survival in response to DCUN1D1 knockdown, consistent with earlier reports that DCUN1D1 knockdown leads to apoptosis in cells." (PMID 24874471, 2014). "DCUN1D1 is amplified and overexpressed in a variety of human cancers." (PMID 30653527, 2019). "DCUN1D1 is an oncogene that increases the efficiency of neddylation, which may lead to a series of diseases, including cancers." (PMID 27285984, 2016). "DCUN1D1 overexpression in cells is sufficient to induce carcinogenesis, suggesting that it may be a bona fide cancer driver gene." (PMID 24874471, 2014). "Cancer-related genes commonly amplified from 3q26 include PIK3CA, TBL1XR1, DCUN1D1, SOX2, MECOM, PRKCI, and TERC." (PMID 34436017, 2021). "The increased proliferation resulting from DCUN1D1 overexpression in cell and animal models, combined with the high prevalence of polyploidy in tumors with DCUN1D1 amplification, suggests the possibility that DCUN1D1’s cancer-promoting activity may result from its effects on abscission." (PMID 30653527, 2019).
tumor (10 papers, 2006 to 2026). "Previous studies demonstrated that DCUN1D1 is associated with the progression and prognosis of PCa and plays a tumour promotive role." (PMID 37566052, 2023). "We have demonstrated that in PCa, blockage of DCUN1D1 inhibits tumour growth in a nude mice model and that, upon inhibition of DCUN1D1, PCa cells lose their ability to proliferate and migrate and they undergo apoptosis." (PMID 37566052, 2023). "To further confirm these observations in primary PCa tumours, we evaluated DCUN1D1 expression levels in human tissue samples." (PMID 37566052, 2023). "After establishing DCUN1D1 as a regulator of PCa carcinogenesis, we evaluated its role in tumour formation." (PMID 37566052, 2023). "Furthermore, we demonstrated that DCUN1D1 regulates PCa cell proliferation, migration and tumour formation in vivo." (PMID 37566052, 2023). "Blockage of DCUN1D1 significantly reduced tumour growth with a 58% reduction in tumour weight." (PMID 37566052, 2023). "The WNT/β-catenin pathway has been shown to play a critical role in cell proliferation, embryonic development and the pro-inflammatory phenotype in the tumour environment, and is consistent with our observations, implicating it in the mechanism of action of DCUN1D1." (PMID 37566052, 2023). "Likewise, tumour development was significantly delayed in DCUN1D1-KD when compared to GFP-KD control cells." (PMID 37566052, 2023). "Since DCUN1D1 impacts several aspects of tumour progression, understanding its mechanism of action is key and may define it as a novel therapeutic target." (PMID 37566052, 2023). "DCUN1D1, a regulator of ubiquitin E3 activity, was significantly increased in NSCLC tumor tissues and positively associated with PD-L1 expression, which leads to enhanced tumor metastasis and poor prognosis of the patients." (PMID 31258527, 2019). "Notably, the DCUN1D1 mutation was unique to the PDX and cell line, suggesting the tumor from which this PDX was derived may have harbored unique genetics that could contribute to increased bortezomib sensitivity." (PMID 32117764, 2020). "Our study shows that miR-218, as a tumor suppressor miRNA, also is a negative regulator of the pro-metastasizing genes SFMBT1 and DCUN1D1." (PMID 27285984, 2016). "To determine whether inhibition of DCUN1D1 affects tumour formation in vivo, we used a xenograft mouse model MF1 where mice were subcutaneously implanted in the right flank with DU145-DCUN1D1-KD or DU145-GFP cells." (PMID 37566052, 2023). "Dysregulation of DCUN1D1, the neddylation pathway and cullin RING ligases’ (CRLs) activity can affect the degradation of specific proteins involved in cellular processes, contributing to oncogenesis, tumour growth and resistance to therapies." (PMID 37566052, 2023). "DCUN1D1 and SOX2 may be co-driver genes of 3q26.3 amplification that synergistically modulate different molecular traits and result in a more aggressive tumor phenotype." (PMID 20126410, 2010).
adenocarcinoma (1 paper, 2023). A common cancer characterized by the presence of malignant glandular cells. "Our RT-PCR analysis demonstrated that DCUN1D1 is upregulated in 42% of the adenocarcinoma tissue samples from stages I, II and III." (PMID 37566052, 2023).
infection (1 paper, 2023). The state of being infected such as from the introduction of a foreign agent such as serum, vaccine, antigenic substance or organism. "Expression of DCUN1D1 was significantly reduced after lentivirus-specific infection." (PMID 37566052, 2023).
prostate (1 paper, 2023). "Together these data clearly indicate DCUN1D1 as a regulator of prostate carcinogenesis." (PMID 37566052, 2023).
DCUN1D1 also shares sentences with these, for which no sentence is quoted: colorectal cancer (2 papers); glioma (2); breast carcinoma (1); esophageal cancer (1); fibrosis (1); gastric cancer (1); glioblastoma (1); liver fibrosis (1); Obesity (1); pancreatic ductal adenocarcinoma (1); synucleinopathy (1); Tinnitus (1).